BRCA2 (BRCA2 DNA repair associated)
Diseases named in the same sentence as BRCA2 in open-access papers (continued):
Sharing a sentence is not in itself a finding about the gene and the disease.
breast cancer (continued). "Three women had bilateral breast cancer with VUS in APC, ATM, and BRCA2, 2 of whom were diagnosed before the age of 50 years." (PMID 33646313, 2021). "Here we saw this behavior in the case of tissue HA levels but also in the case of some of colorectal and breast cancer patients for the expression of BRCA1 and BRCA2." (PMID 32610620, 2020). "A total of 7 mutations were detected in BRCA2 whole-genome sequencing, including 5 non-significant mutations (3623A>G, 4034T>C, 4790A>G, 6740G>C, 7469A>G); one no-record mutation (1716T>A), and 1 recorded mutation (1342A>C), which was associated with breast cancer and ovarian cancer." (PMID 32356124, 2020). "A total of 7 mutations were detected in the whole gene sequencing of BRCA2, among which 5 were non-significant mutations (3623A>G, 4034T>C, 4790A>G, 6740G>C, 7469A>G), one mutation (1716T>A) not recorded, and one recorded mutation (1342A>C) associated with breast cancer and ovarian cancer." (PMID 32356124, 2020). "Of note, deletions at 13q (BRCA2 and RB1) commonly identified in breast cancer were discovered in 3/5 (60%) CTC samples." (PMID 32650480, 2020). "There is clearly a very high rate of contralateral breast cancer approaching 4%–7% annually and significantly higher than BRCA1 or BRCA2 in those diagnosed aged <35." (PMID 33327514, 2020). "Abnormal expression of BRCA1, BRCA2, and PALB2 has been observed in about 10% of breast cancer cases." (PMID 32824813, 2020). "There are many risk factors for developing breast cancer, for example, the occurrence of mutations in the BRCA1 and BRCA2 genes, hormone therapy during menopause, first menstruation at an early age, late motherhood or no children, older age, and a positive family history of breast cancer." (PMID 32015564, 2020). "Breast cancers in BRCA2 carriers are predominantly ER-positive, in contrast to BRCA1 carriers, who mainly present with basal-like (ER-negative) breast cancers." (PMID 32939053, 2020). "Finally, the lack of sensitivity to the PARP inhibitor Olaparib observed in our cell lines has important clinical implications as breast cancer patients carrying these variants are not predicted to respond to PARP inhibitor treatment (unlike BRCA2-mutated tumors that are HR-deficient)." (PMID 32286328, 2020). "High-penetrance breast cancer genes, such as BRCA1 and BRCA2, are routinely diagnosed in clinical practice in many countries." (PMID 32823908, 2020). "Susceptibility genes with high or moderate penetrance (i.e., BRCA1, BRCA2, PALB2, ATM, and CHEK2) have been identified in 30 to 40% of patients with a family history of breast cancer, but only in 5% of sporadic breast cancer cases." (PMID 33126731, 2020). "The breast cancer prospective cohort included 2088 BRCA1 carriers with 297 incident cases and 1757 BRCA2 carriers with 215 incident cases." (PMID 32665703, 2020). "Most cases of breast cancer related to BRCA1 and BRCA2 are diagnosed in young women, and the probability of pregnancy in young women is high." (PMID 33379383, 2020). "Genomic DNA was extracted from peripheral blood sample of a young woman affected with breast cancer belonging to a HBOC family and the entire coding regions of the BRCA1 and BRCA2 genes were amplified using the Ion AmpliSeq BRCA1 and BRCA2 Panel." (PMID 33159495, 2020).
breast cancer (continued). "Earlier, in vitro data in breast cancer cell lines demonstrated an increase in BRCA1 and BRCA2 mRNA expressions with DHA treatment, suggesting a transcriptional or post-transcriptional regulation of these genes by DHA." (PMID 32498320, 2020). "A systematic review of the cost-effectiveness of healthcare programs involving genetic testing of the two major breast cancer genes, BRCA1 and BRCA2 indicated that family history-based screening programs are cost-effective." (PMID 32231682, 2020). "In this multicenter, retrospective, matched cohort study, we investigated whether women with an inherited mutation in BRCA1 or BRCA2 experience more severe hematologic toxicities during curative intent chemotherapy for breast cancer than similar women without a mutation." (PMID 31407530, 2019). "Sixty-eight percent of breast cancers occurring in BRCA1 carriers were triple-negative, compared to only 16% of breast cancers in BRCA2 carriers." (PMID 30980249, 2019). "Only nodal involvement remained significant in the comparison between BRCA2 and non‐BRCA breast cancer cases in the multivariable model (ORBRCA2 vs non‐BRCA: 2.54 [1.20–5.37)." (PMID 30175445, 2019). "Therefore, features of genomic instability such as that mediated by BRCA1- and BRCA2- deficiency in breast cancer were necessary, but not always sufficient, for yielding T cell-inflamed tumour microenvironment, and by extension, predicting clinical benefit from immunotherapy." (PMID 31022191, 2019). "The BRCA1 (OMIM accession number 113705) and BRCA2 (OMIM accession number 600185) (BRCA1/2) genes are the earliest discovered and most studied genes that are related to breast cancer." (PMID 30968603, 2019). "It is well-known that poly ADP-ribose polymerases (PARPs) form SL interactions with the two breast cancer genes BRCA1 and BRCA2." (PMID 31870274, 2019). "It has been found that in MCF-7 and MDA-MB human breast cancer cells, n-3 PUFAs can effectively promote the expression of breast cancer suppressor genes BRCA1 and BRCA2." (PMID 31182104, 2019). "In this report, we analyzed Mexican population data from a sample of 3985 outbred individuals, and additional 66 hereditary breast cancer patients were analyzed in order to better define the spectrum of common genomic variation of the BRCA1 and BRCA2 genes." (PMID 30630528, 2019). "Finally, we sought to define whether PALB2-associated breast cancers with bi-allelic PALB2 inactivation would differ from breast cancers arising in BRCA1 and BRCA2 pathogenic germline mutation carriers with bi-allelic inactivation of BRCA1 and BRCA2, respectively." (PMID 31428676, 2019). "This study also confirmed the utility of NGS for performing the genetic testing of hereditary breast cancer based on BRCA1 and BRCA2 genetic alterations." (PMID 31131559, 2019). "It is possible that members of the FA core complex that act upstream of HRR are less relevant for breast cancer due to their more specialized function in the repair of crosslinks while BRCA1, BRCA2, and PALB2 function more globally at DNA double-strand breaks." (PMID 31467304, 2019). "Estimates are that about 1.1–1.7% of women with breast cancer have a PV in CHEK2, 1.4–2.1% in BRCA1, 1.6–2.2% in BRCA2, 0.87–1% in ATM, and 0.84–0.87% in PALB2, with other genes less than 1%." (PMID 30832243, 2019). "Of the 5,099 breast cancer patients, 92 (1.8%) were identified as BRCA1/2 carriers (50 BRCA1 carriers and 42 BRCA2 carriers) and 5,007 were non‐BRCA." (PMID 30175445, 2019).
breast cancer (continued). "A recent prospective cohort study has estimated that the cumulative risks of breast cancer to age 80 years was 72% for BRCA1 and 69% for BRCA2 carriers." (PMID 31065452, 2019). "In our result, the average age at breast cancer onset between the BRCA1 group and BRCA2 group was nearly equal." (PMID 31143373, 2019). "One hundred four families with a history of breast cancer were sampled in different regions of Colombia, and the BRCA1 gene and exon 11 of the BRCA2 gene were sequenced." (PMID 31341521, 2019). "The benefit of red wine intake to some women with breast cancer was evident in observational studies and was attributed to the binding of resveratrol to the oestrogen receptor, which promotes BRCA1 and BRCA2 protein transcription." (PMID 31505792, 2019). "It has been recently estimated that the cumulative risks of breast cancer to age 80 years was 72% for BRCA1 and 69% for BRCA2 carriers." (PMID 31741787, 2019). "The breast cancer 1 (BRCA1) and breast cancer 2 (BRCA2) genes normally behave as tumor suppressor genes and can maintain cell proliferation and differentiation." (PMID 31182966, 2019). "Among the 8 patients with left breast carcinomas, the BRCA1 and BRCA2 were positive in 3 patients (27.2%) and 5 patients (62.5%), respectively." (PMID 30713775, 2019). "Among the 3 germ line mutation, 2 were similar to that observed in the NTM patients with breast cancer history (chromosome position: 41245471, BRCA1; 32906729, BRCA2)." (PMID 30054559, 2018). "Gene-panel testing of BRCA1, BRCA2, PALB2 and RNASEL in the Australian Breast Cancer Family Registry identified five carriers of RNASEL:p.Glu265* in 591 early onset breast cancer cases." (PMID 29422015, 2018). "Two genetic markers, not often used to describe a type of breast cancer, but rather to estimate an individual's predisposition to developing it, are the breast cancer 1 and breast cancer 2 (BRCA1 and BRCA2) genes." (PMID 29713580, 2018). "While 90–95% of breast cancer cases occur sporadically, approximately 5–10% are hereditary, with breast cancer gene 1 and 2 (BRCA1 or BRCA2 hereafter) being the most common." (PMID 30001421, 2018). "The cumulative lifetime risk of developing breast cancer associated with a BRCA1 or BRCA2 mutation, up to age 80, may be as high as 72% and 69%, respectively, and approximately 5–10% of newly diagnosed breast cancers are thought to be attributable to a BRCA1 or BRCA2 mutation." (PMID 29752676, 2018). "Despite these specificities, the majority of breast cancer genetics studies performed in North Africa remain restricted to the investigation of the BRCA1 and BRCA2 genes." (PMID 29879995, 2018). "When detected outside of the dedicated follow-up programs, the prognosis is bad for breast cancer in both BRCA1 and BRCA2 carriers." (PMID 28939999, 2018). "Moreover, POFT cancer women with breast cancer as the SPC might have a higher possibility of BRCA1 or BRCA2 germline mutation compared to women without breast cancer." (PMID 30089478, 2018). "Finally, additional screening for breast cancer and risk-reducing interventions through chemoprevention and surgical procedures can be undertaken by the individual and family members who are known BRCA1 or BRCA2 germline mutation carriers to prevent future cancers." (PMID 29506471, 2018). "Those genes are the epidermal growth factor receptor (EGFR) and the breast cancer genes BRCA1 and BRCA2." (PMID 30546831, 2018). "In Egypt, 60 breast cancer patients, derived from 60 families, were selected for molecular genetic testing of BRCA1 and BRCA2 genes." (PMID 29409476, 2018). "After two decades since the discovery of the BRCA1 and BRCA2 genes, genetic testing for hereditary breast and ovarian cancer (HBOC) has become a standard practice for breast cancer patients." (PMID 30001421, 2018). "The subsequent breast cancer analyses focus on the updated ER-negative breast cancer PRS for BRCA1 carriers and the updated overall breast cancer PRS for BRCA2 carriers." (PMID 28376175, 2017).
breast cancer (continued). "The intervention trial examined methylation level across 45 sites within a panel of 21 breast cancer-related genes (including 4 sites in BRCA1 and 1 site in BRCA2)." (PMID 28594926, 2017). "It is now apparent that mutations of several other genes, such as BARD1, PALB2 (Partner And Localizer Of BRCA2) and BRIP1 (BRCA1 Interacting Protein C-Terminal Helicase 1), contribute to familial breast cancer." (PMID 29292755, 2017). "As an example, as recently as 5 years ago, a breast cancer patient who also has family history of young onset breast cancer would likely be tested in a healthcare setting for two genes (BRCA1 and BRCA2)." (PMID 29259772, 2017). "In this study, we evaluated the antioxidant potential and the influence of pitaya extract (PE) on cell viability, colony formation, cell cycle, apoptosis, and expression of BRCA1, BRCA2, PRAB, and Erα in breast cancer cell lines (MCF-7 and MDA-MB-435)." (PMID 28761624, 2017). "In theory, another possibility is that consanguinity protects against breast cancer by decreasing the number of BRCA1 and BRCA2 cancer cases as homozygotes of these genes are early aborted." (PMID 29157216, 2017). "Taken together, 13 out of 20 mutation carriers in this cohort actually fulfilled the Swedish BRCA testing criteria at time of breast cancer diagnosis (7 BRCA1 and 6 BRCA2)." (PMID 28120249, 2017). "The spatial localization of BRCA1, BRCA2, RAD51, agrees with the known specificity of these genes to breast cancer, and physical or predicted interactions with each other." (PMID 28326099, 2017). "Notably, BRCA2 p.Arg2108Cys was evaluated as pathogenic in spontaneous homologous recombination, but our study suggests that this variant is unlikely to be associated with high risk of breast cancer." (PMID 28222693, 2017). "Among unselected breast cancer cases, 3.3% tested positive for BRCA1/3450del4, 2.2% for BRCA1/A1708E, 1.1% for BRCA2/3034del4, and 0.4% for BRCA2/1991del4." (PMID 28680148, 2017). "Our French Canadian cohort comprised three major familial breast cancer subgroups namely BRCA1 and BRCA2 carriers as well as BRCAX individuals, i.e. non BRCA1/2 (affected and unaffected)." (PMID 29108258, 2017). "Women who have a positive family history of breast carcinoma are 2–4 times more likely to develop the cancer, especially the females who are the carriers of BRCA1 or BRCA2 genes have the significant chance to develop carcinoma of breast." (PMID 28969709, 2017). "Indeed, our previous study have revealed among 40 breast cancer patients, at increased risk of carrying a mutation, 29 women with negative BRCA1/2 testing and 11 patients with a positive BRCA1/2 status including six patients with BRCA1 mutation and five patients carrying BRCA2 mutation." (PMID 27129401, 2016). "While in a study with a larger sample size of 99 Chinese patients with hereditary breast cancer, 7.1% in BRCA1 and 11.1% in BRCA2 were found by NGS." (PMID 27257965, 2016). "Approximately 56% of these genes have been previously identified as up-regulated at 24 h post-estrogen stimulation, including known breast cancer genes BRCA1, BRCA2, and E2F1." (PMID 27539783, 2016). "We compared the VNTR genotype distributions in the XRCC5 promoter between three types of familial breast cancer: BRCA1+, BRCA2+, and BRCAx." (PMID 27148484, 2016). "Mammary tissue during puberty and pregnancy from these mice have a similar two–three-fold HDR defect as in other proliferative tissue types, including small intestine epithelium, suggesting that an HDR defect per se may not confer tissue specificity for BRCA2-associated breast cancers." (PMID 27779185, 2016). "In this study, BRCA1 mutation rate is identical to BRCA2 mutation rate; this result may be due to the small number of patients analyzed but if this finding is confirmed in elevated sample, the BRCA1/2 mutations may contribute similarly to early-onset breast cancer in Algeria." (PMID 26997744, 2016).
breast cancer (continued). "Because of the critical role of FOXC1 in BLBC cell function, along with an opposing expression pattern between BRCA1- and BRCA2-mutant breast cancers, it is speculated that BRCA1, not BRCA2, mutation-elicited signaling might synergize with FOXC1 action in mammary tumorigenesis." (PMID 27708239, 2016). "However, some trends could be observed, for example, all of the women with mutations in the BRCA2 gene with bilateral breast cancer were homozygous for the G allele in rs132281615, and among those with mutations in BRCA1 and with bilateral breast cancer, 86 % had at least one G allele." (PMID 26770289, 2016). "Pathogenic variants were identified in 11.8% (6/51) of male patients with breast cancer and were found in BRCA1, BRCA2, CHEK2, and PALB2; one man was positive for both a BRCA1 and CHEK2 variant." (PMID 26681312, 2016). "The average ages at breast cancer diagnosis among the groups were 41.4 (BRCA1+), 43.6 (BRCA2+), and 47.7 (BRCAx)." (PMID 27148484, 2016). "Compared to sporadic breast cancers, both BRCA1- and BRCA2-related breast cancers are more likely to be high grade and poorly differentiated." (PMID 26496879, 2015). "The use of PARPinh in monotherapy to treat patients with breast cancer defective in BRCA1 and/or BRCA2 is a clear example of what is known as synthetic lethality." (PMID 26056084, 2015). "We divided the 21 patient datasets into 3 breast cancer types: 12 sporadic (i.e., tumors WT/WT for both BRCA1 and BRCA2), 5 BRCA1, and 4 BRCA2 mutant tumors." (PMID 25699710, 2015). "The estimated carrier frequency for women diagnosed with breast cancer under 50 years of age, at 0.5%, is lower than that estimated for BRCA1/BRCA2 carriers in the same population." (PMID 25925845, 2015). "This was significantly higher autoantibody responses to PARP1 and BRCA1/BRCA2 (especially to PARP1 and BRCA1) in ovarian cancer and breast cancer compared to normal control sera (P < 0.001 and P < 0.01)." (PMID 25865228, 2015). "Other relevant genes also contribute to inherited breast cancer, among these genes is PALB2 (Partner and Localizer of BRCA2) gene." (PMID 26489409, 2015). "However, we do not expect significant differences between BRCA1 and BRCA2 mutation carriers in choice of (risk reducing) breast surgery, since both groups probably received similar information about the risk of (contralateral) breast cancer." (PMID 25700605, 2015). "Compared to the BRCA1 and BRCA2 profiles reported in literature and our previous study, copy number aberrations are infrequently seen in CHEK2*1100delC breast cancers." (PMID 26553136, 2015). "In this study we have performed high-resolution copy number, LOH and gene expression profiling of 120 familial breast carcinomas selected from a larger cohort of 155 familial breast tumors, including BRCA1, BRCA2 and CHEK2 mutant tumors." (PMID 26553136, 2015). "We performed high-resolution SNP array and gene expression profiling of 120 familial breast carcinomas selected from a larger cohort of 155 familial breast tumors, including BRCA1, BRCA2, and CHEK2 mutant tumors." (PMID 26553136, 2015). "In English Springer Spaniels with mammary tumors, BRCA1 and BRCA2 genes seem to be involved in the development of the tumor." (PMID 24641873, 2014). "The first FANCJ mutants to be studied were missense variants (P47A, M299I) identified in individuals with early breast cancer and normal genotypes for BRCA1 or BRCA2." (PMID 25374583, 2014). "Here, we describe an Italian family with a high number of cases of breast cancer and other types of tumour subjected to the MLPA test to verify the presence of BRCA1, BRCA2 and CHEK2 deletions and duplications." (PMID 24986639, 2014). "The results revealed that the compounds were docked more firmly and inhibited the breast cancer related BRCA1 and BRCA2 oncoproteins and COX-2 and COX-1 inflammatory proteins." (PMID 25254204, 2014).